DDX1 (DEAD-box helicase 1)
Diseases named in the same sentence as DDX1 in open-access papers (continued):
Sharing a sentence is not in itself a finding about the gene and the disease.
cancer (16 papers, 2012 to 2026). A tumor composed of atypical neoplastic, often pleomorphic cells that invade other tissues. "Notably, the expression of DDX1 was reported to decrease under hypoxic conditions, and intratumor hypoxia is associated with cancer metastasis and, consequently, patient mortality." (PMID 30279964, 2018). "Thus, DDX1-MYCN coamplification is present in a considerable fraction of cancers and is associated with aberrantly high DDX1 expression, which could affect cancer cell physiology." (PMID 38197697, 2024). "In line with altered α-KGDH activity, cancer cells with DDX1-MYCN coamplification had higher levels of citrate, isocitrate, and α-KG." (PMID 38197697, 2024). "FAM98B is an arginine methyltransferase utilized in tumorigenesis and works in tandem with DDX1, a pan-cancer marker, in RNA metabolism/processing." (PMID 36873459, 2022). "Using the ENCODE database, we subsequently found binding peaks of ZBTB11 in the promoter regions of DDX1 in human cancer K562 and MCF‐7 cells." (PMID 36054300, 2022). "miR-17, known as an onco-miRNA in cancer development, was identified to be one of the potential common targets of circLONP2 and DDX1." (PMID 32188489, 2020). "Among them, DDX1 is frequently co-amplified with N-myc in several types of cancers and plays a crucial role in testicular tumorigenesis." (PMID 29535419, 2018). "We propose that pharmacologic mTORC1 inhibition could provide an effective therapy for a meaningful fraction of cancer patients with DDX1-MYCN coamplification." (PMID 38197697, 2024). "DDX1-MYCN coamplification also occurred in several other cancer entities." (PMID 38197697, 2024). "By mining The Cancer Genome Atlas data, we found that the mRNA levels of ZBTB11 and DDX1 were positively correlated in BC tissues." (PMID 36054300, 2022). "No DDX1 amplifications without MYCN were detectable in 556 cancer genomes." (PMID 38197697, 2024).
tumor (14 papers, 2004 to 2026). "We found that DDX1 expression was positively associated with the T stage of the tumor (P = 0.003), pathologic stage (P < 0.001), and histologic grade of HCC (P = 0.02)." (PMID 36451087, 2022). "Comparing with normal tissues, the expression level of DDX1 was significantly de-regulated in tumor tissues." (PMID 36478716, 2022). "DDX1 is ubiquitous in the cell and is involved in viral replication and overexpressed in tumour cells." (PMID 26323305, 2015). "The human RNA helicase DDX1 in the DEAD-box family plays an important role in RNA processing and has been associated with HIV-1 replication and tumour progression." (PMID 26323305, 2015). "MYCN-MB fusion transcripts were unique to each tumor; 2 recurrent fusion-partner genes, DDX1 and NBAS (immediately upstream of MYCN41) were involved in fusions with each other and additional partners (MYCNOS) in 3 MYCN-MBGrp3/4 tumors, but fusion position and gene order were not conserved." (PMID 39377358, 2025). "In addition, univariate Cox regression analysis showed significant relationship of pathologic stage, DDX1 expression (hazard ratio = 1.628, 95% CI = 1.145–2.313, P = 0.007), T stage, M stage, and tumor status with poor OS." (PMID 36451087, 2022). "However, additional experimental and theoretical studies are needed to validate the relationship between DDX1 and tumor infiltration." (PMID 36451087, 2022). "Thus, DDX1 methylation examination has the potential to be developed as a screening tool for predicting tumor status and progression; however, further in vivo and in vitro experiments are needed." (PMID 36451087, 2022). "Additionally, multivariate Cox regression analysis identified DDX1 gene expression (HR = 1.822, 95% CI = 1.139–2.915, P = 0.012) and tumor status (HR = 1.873, 95% CI = 1.172–2.995, P = 0.009) as independent risk factors of total survival for patients with HCC." (PMID 36451087, 2022). "In addition, we found DDX1 expression level was lower in late stage and grade tumor tissue." (PMID 36478716, 2022). "DHX9 family members, such as DDX1, DDX3, and DDX5 are considered as oncogenes to promote proliferation of tumor cells." (PMID 37305700, 2023). "To date, three genes have been identified that are frequently co-amplified with MYCN in NBs: DDX1 in 50% of the cases, NAG in 20% of the tumours, and MYCNOS in all cases." (PMID 19615087, 2009). "Our data suggest that high DDX1 expression impedes the TCA cycle as well as OXPHOS and consequently promotes accumulation of α-KG, which in turn triggers mTORC1 activation to maintain tumor cell survival." (PMID 38197697, 2024). "Because cisplatin‐based chemotherapy mainly induces double‐strand breaks and apoptosis in tumour cells, suppressing the ZBTB11/DDX1 signalling axis may increase the cisplatin sensitivity of BC cells." (PMID 36054300, 2022). "Moreover, the Tumor Immune Estimation Resource dataset and QUANTISEQ algorithm revealed that DDX1 expression positively correlates with immune infiltrating cells." (PMID 36451087, 2022). "However, survival analyses in a large study using 75 MYCN-amplified tumours indicate that neither amplified DDX1 nor NAG have an additional adverse effect on the prognosis of the patients." (PMID 19615087, 2009).
infection (5 papers, 2017 to 2025). The state of being infected such as from the introduction of a foreign agent such as serum, vaccine, antigenic substance or organism. "These pulldowns also verified that TOP2B associates with DDX1, FAM98A, and RTCB, suggesting a potential role for this isoform in RNA metabolism during infection." (PMID 40557872, 2025). "The RNA-binding activity of several proteins increased throughout the infection, such as DDX1, DDX3X, DDX5, and HNRNPA1, indicating that SARS-CoV-2 requires these proteins in the replication and transcription processes." (PMID 37314180, 2023). "The expression levels of some ISGs (IFIT1, IFIT2, IFIT3) and proinflammatory cytokines (IL-6, IL-8) in DDX1-knockdown cells were analyzed after TGEV infection." (PMID 28848548, 2017). "To enhance the formation of AVGs, we silenced the expression of E3 and assessed the localization of DDX1, FAM98A, and RTCB at 6–8 h post infection." (PMID 40557872, 2025). "Nullbasic also inhibits Rev-dependent viral mRNA transport from the nucleus by binding to DEAD/H-box helicase 1 (DDX1) and inhibiting reverse transcription, leading to accelerated uncoating kinetics post infection and defective viral DNA synthesis." (PMID 38140676, 2023).
bone disorder (1 paper, 2024). "Notably, genes such as CSRP2, DDX1, RHBDL1, SEZ6L, and CTSK are involved in growth, development, locomotion, and bone disorders." (PMID 38788487, 2024).
DDX1 also shares sentences with these, for which no sentence is quoted: retinoblastoma (5 papers); Neurological Disorder (2); prostate carcinoma (2); Brain Tumour (1); cervical carcinoma (1); colorectal cancer (1); diabetes (1); embryonal tumours (1); hepatocellular carcinoma (1); Hypertension (1); Insulin resistance (1); ischemia (1); ischemic stroke (1); Obesity (1); testicular tumours (1).